TIMP3 (TIMP metallopeptidase inhibitor 3)
Diseases named in the same sentence as TIMP3 in open-access papers (continued):
Sharing a sentence is not in itself a finding about the gene and the disease.
tumor (continued). "It is a molecular target of mAb NJ001 in the regulation of TIMP‐3 expression, further inhibiting tumor invasion." (PMID 32744429, 2020). "Many studies indicated that by targeting Pten and Timp3 tumor suppressors, miR-221&222 induced TRAIL resistance and enhanced cellular migration through activating the AKT pathway." (PMID 32122385, 2020). "Melatonin, alone or in combination with vinorelbine, also increased TIMP3 expression, an inhibitor of angiogenesis that limits vessel density close to tumors and reduces tumor growth." (PMID 32179814, 2020). "Numerous studies show that miR-21-5p promotes carcinogenesis and tumor progression by targeting genes encoding PDCD4, PTEN, BTG2, FasL, IGFBP3, TGF-β1, FBXO11, and TIMP3." (PMID 33396321, 2020). "miR-221 is also associated with apoptosis by targeting tumor suppressors such as PTEN and TIMP3 by activating the AKT pathway and metallopeptidase expression in HCC." (PMID 33171811, 2020). "We aimed to measure ELN gene expression and its related MMP9, MMP12 and TIMP3 gene levels in tumor from CRC patients compared to adjacent non-tumor tissues and healthy controls in existing array datasets." (PMID 32171282, 2020). "TIMP‐3 is a possible tumor suppressor gene, which can tightly bind to the extracellular matrix and has been shown to inhibit tumor angiogenesis, invasion, and metastasis." (PMID 32744429, 2020). "On the other hand, TIMP3 was proved to function as a tumor‐suppressor by blocking the binding between VEGF and VEGFR and modulating extracellular matrix (EM) production, an important player in angiogenesis." (PMID 32896063, 2020). "Tissue inhibitors of metalloproteinase 3 (TIMP3) are a major endogenous inhibitor of matrix metalloproteinase (MMPs) that inhibit tumor growth, invasion, metastasis and angiogenesis." (PMID 31588243, 2019). "Phenelzine-treated macrophages also significantly increased TIMP3, which is a potent tumor angiogenesis and growth inhibitor." (PMID 31249575, 2019). "MiRNA-21 is another BC-related miRNA that promotes in-vitro and in-vivo tumour growth by targeting PTEN and TPM1 tumour-suppressor genes, whereas it affects metastasis by directly targeting TIMP3, SERPIN5B, PDCD4 and BCL28,9." (PMID 31811234, 2019). "In other studies, plasma levels of LCN2/matrix metallopeptidase 9 complex, MMP2, TIMP1, TIMP2 and TIMP3 were correlated to tumor size, lymph node involvement, tumor differentiation and prediction of tumor stage and T status in patients affected with HNSCC." (PMID 31014274, 2019). "In this study, we demonstrated that MPT0B390 induces TIMP3 to inhibit CRC tumor migration, invasion and angiogenesis in vitro and in vivo." (PMID 31588243, 2019). "This can be largely attributed to diverse MMP-dependent and MMP-independent functions of TIMP3 and the influence of tumor microenvironment on its expression and activity." (PMID 30988064, 2019). "SFN (10 μmol/kg body weight; three times per week) inhibited tumour growth, an effect which was associated with reduced expression levels of matrix metalloproteinases, increased expression levels of TIMP3 (Metalloproteinase inhibitor 3) and enhanced apoptosis." (PMID 31003534, 2019). "Artificial modulation of TIMP3 was performed to explore the role of TIMP3 in tumor metastasis in vitro and in vivo." (PMID 31624299, 2019). "PTEN, TIMP3 (tissue inhibitor of metalloproteinases 3), p27, and p57 are well-known tumor suppressor genes, but their expressions are often dysregulated in human cancer." (PMID 31929798, 2019). "We generated lentivirus-infected TIMP3 knockdown HCT116 stable clones and found that MPT0B390-inhibited tumor cell migration can be abrogated by TIMP3 blockage." (PMID 31588243, 2019). "Taken together, these results indicated that MPT0B390 suppresses tumor metastasis by up-regulating TIMP3 expression in vitro and in vivo." (PMID 31588243, 2019). "High expression of TIMP3 has been found to promote apoptosis in various tumor types in vitro and in vivo." (PMID 31588243, 2019).
tumor (continued). "TIMP3 plays a crucial role in promoting apoptosis in prostate cancer cells and inhibits the migration and invasion abilities of tumor cells in osteosarcoma." (PMID 31624299, 2019). "With respect to response to neoadjuvant therapy, however, only Tissue Inhibitor of Metalloproteinases 3 (TIMP3) methylation status was significantly different across four tumor regression grade classes." (PMID 31390840, 2019). "TIMP3, a tumor suppressor that inhibits matrix metalloproteinases and angiogenesis, has an uncertain role in PanNET tumorigenesis owing to contrasting reports about its methylation state." (PMID 30657883, 2019). "According to our previous work, sulfonamide-based HDAC inhibitors increased TIMP3 expression to inhibit tumor angiogenesis." (PMID 31588243, 2019). "Several other studies have demonstrated that changes of TIMP-3 expression have been significant in tumor growth, invasion and metastasis." (PMID 29467412, 2018). "TIMP3 is an inhibitor of extracellular matrix metalloproteinase that can suppress angiogenesis, tumor growth, and invasion and migration." (PMID 29796115, 2018). "We showed that methylation of TIMP-3 was decreased in the tumor tissues of the IL-32γ mice than in the wild type mice by qPCR." (PMID 29467412, 2018). "TIMP-3 has been known to act as a tumor suppressor gene to inhibit tumor growth, invasion, and angiogenesis." (PMID 29467412, 2018). "There was significant inverse correlation between TIMP3 expression and blood vessel density in the tumor (p = 0.031)." (PMID 29304854, 2018). "In the tumor tissue of IL-32γ overexpressed transgenic mice, the methylation of TIMP-3 was inhibited." (PMID 29467412, 2018). "Changes of TIMP-3 expression by methylation have been significant in tumor growth, invasion and metastasis." (PMID 29467412, 2018). "Agreeing with IHC data, the protein level of TIMP-3 was increased in the tumor tissues of the IL-32γ mice than in the wild type mice by Western blotting." (PMID 29467412, 2018). "In comparison, the volume of the tumor formed by Saos2-lung cells with TIMP3 overexpression had decreased considerably compared to that of the scramble group, which was in accordance with our in vitro data." (PMID 29731768, 2018). "In terms of mechanism, cSMARCA5 enhanced the expression of tissue inhibitor of metalloproteinase 3 (TIMP3), a well-known tumor suppressor, by sponging miR-17-3p and miR-181b-5p." (PMID 30072625, 2018). "Growing evidences have demonstrated that expression of TIMP-3 is significant in the development of tumor and its expression is reduced in lung tumor patients." (PMID 29467412, 2018). "In an in vivo carcinogen induced lung tumor model, tumor growth was inhibited in IL-32γ overexpressed mice with elevated TIMP-3 expression and hypomethylation accompanied with reduced NF-κB activity." (PMID 29467412, 2018). "Alternatively, it has been proposed that miR-21 downregulates expression of programmed cell death 4 (PDCD4) and tissue inhibitor of metalloproteinase (TIMP3), both of which function as tumor suppressors." (PMID 29069873, 2017). "TIMP3 is an extracellular matrix-bound protein, which regulates matrix composition and affects tumor growth." (PMID 29236770, 2017). "TIMP3 is hypermethylated in OS tumor tissues compared with normal tissues and has been identified as a tumor suppressor that plays essential roles in the inhibition of tumor angiogenesis." (PMID 28477009, 2017). "Six tumor-associated genes (RASSF1A, APC, BVES, TIMP3, GSTP1, and HOXA9) were selected as candidates." (PMID 28951629, 2017). "miR-708-5p expression also negatively correlated with two tumor suppressors, metalloproteinase inhibitor 3 (Timp3) and metastasis suppressor protein 1 (Mtss1) levels, leading the authors to conclude miR-708-5p acts as a transformative promoter in liver cells." (PMID 29050362, 2017).
tumor (continued). "The ectopic expression of miR-29a promotes angiogenesis and tumor cell proliferation through the down-regulation of anti-angiogenic genes such as Col4a2, Spry1 and Timp3." (PMID 28388561, 2017). "After 7 months of HFD, Timp3 overexpression resulted in decreased HCC progression demonstrated by significantly reduced tumor number and size." (PMID 28751722, 2017). "Timp3 inhibits MMPs important for cell migration and has tumor suppressive roles in HCC, yet Timp3-/- mice have decreased incidences of HCC compared to wild-type mice after exposure to carcinogens." (PMID 29050362, 2017). "According to this, our work showed that TIMP3 expression was down regulated not only in the ARF−/− tumor xenograft, but also in TAMs isolated from the tumors of ARF−/− mice or in ARF−/− macrophages exposed to the CM from B16F10 tumor cells." (PMID 27572316, 2016). "Here we demonstrate that KDM1A advances tumor metastasis by epigenetically silencing the TIMP3 transcription, which in turn stimulates MMP2 expression and JNK phosphorylation." (PMID 27058897, 2016). "We have focused our attention on TIMP3 because of its unique ability to induce apoptosis in normal and tumor cells in vitro." (PMID 26655503, 2016). "MPT0G013, a novel HDAC inhibitor, was reported by our colleague to inhibit tumor angiogenesis through up-regulation of TIMP3 expression." (PMID 26587975, 2016). "TIMP3 is related to tumor development and in particular has been shown to antagonize the activity of matrix metalloproteinases as well as to inhibit tumor growth, angiogenesis, invasion, and metastasis." (PMID 27410681, 2016). "Our data show that mRNA expression and protein levels of TIMP-3 were decreased in ARF−/− tumor xenografts compared to WT tumor xenografts." (PMID 27572316, 2016). "Because of reduced growth and anti-angiogenic activity, TIMP3 is considered to be a tumor suppressor in various tumors." (PMID 26872030, 2016). "Despite delayed tumor initiation and decreased tumor numbers in Timp3−⁄− mice, the most advanced tumor reached experimental endpoint at the same time as in PyMT Timp3+/+ mice." (PMID 25807548, 2015). "In contrast, when PyMT day 40 cells were transplanted, tumors became palpable over a span of 50–120 days in Timp3+/+ control recipients, but the same tumor cells showed a delay in growth upon transplantation in Timp3 deficient hosts." (PMID 25807548, 2015). "These oncogenic miRNAs confer resistance to tamoxifen through down-regulation of tumor suppressors p27Kip1 and TIMP3." (PMID 26206152, 2015). "Some researchers presumed that EFEMP1 regulated matrix composition and negatively affects tumor growth, invasion and angiogenesis by interacting with TIMP-3 and downregulating MMPs." (PMID 25987128, 2015). "Specifically, 36% of Neu Timp3−⁄− mice remained tumor free across their lifespan, even beyond >2 years of age." (PMID 25807548, 2015). "It inhibits MMP-2, MMP-3, TIMP-1, and TIMP-3 in preventing tumor angiogenesis, and MMP-9 through an autocrine loop in blocking lung and liver metastasis mediated by stromal fibroblasts." (PMID 25909283, 2015). "Comparison of mammary weights in 80-day-old mice reflected a marked reduction in tumor multiplicity and burden in Timp3 null mice, which was visualized by the overall decreased cellularity evident in wholemount staining." (PMID 25807548, 2015). "Tumor progression to end-point in PyMT Tnfr1-/- mice was also comparable to PyMT Timp3−⁄− and PyMT Tnfr1−⁄− cohorts." (PMID 25807548, 2015). "Then, we examined other tumor-associated genes, such as c-myc, E-cadherin, TIMP-2, TIMP-3, and VASH1." (PMID 26452129, 2015). "Tumor initiation was delayed in PyMT Timp3+/−and Neu Timp3+/− cohorts compared to their respective control groups." (PMID 25807548, 2015). "Tumors of cells transfected pre-implantation with the anti-miR-21 LNA had significantly decreased tumor growth and increased TIMP3 protein expression." (PMID 25587717, 2015).
tumor (continued). "This was true for both PyMT Timp3+/+ (p = 0.0114) and PyMT Timp3−⁄− donor cells (p = 0.0717), and importantly, 50–60% of these Timp3−⁄− experimental recipients remained tumor free at 120 days." (PMID 25807548, 2015). "Together our data is the first to identify a tumor promoting role of endogenous Timp3 in vivo, the spatial and temporal windows of this effect, and its dependence on Tnfr1." (PMID 25807548, 2015). "In our study, the comparison between tissues showed an increase of RASSF1A and TIMP3 methylation in tumor in all experimental groups." (PMID 26401660, 2015). "Treatment of tumor cells with a linked nucleic acid antagomir to miR-21 inhibited tumor growth and increased tumor expression of TIMP3 in vivo in 01B74 Athymic NCr-nu/nu mice." (PMID 25587717, 2015). "In the aggressive PyMT model, we noted a remarkable delay of tumor initiation and metastasis in the Timp3 null group." (PMID 25807548, 2015). "TIMP-3 promotes apoptosis in tumor cells through the stabilization of cell surface death receptors and the activation of caspase-8." (PMID 25171061, 2014). "According to univariate analysis, several items were correlated with both disease-free survival and overall survival of HCC, including TIMP-3 expression, tumor size, portal vein invasion, lymph node metastasis and the TNM stage." (PMID 25171061, 2014). "Under pathological conditions, TIMP3 has been demonstrated as a potent inhibitor of angiogenesis and tumor growth." (PMID 25226613, 2014). "Taken together, these results indicate that MPT0G013 abrogates growth factor-induced angiogenesis by up-regulating the antiangiogenic protein TIMP3 in vitro and in vivo, and leads to tumor growth inhibition." (PMID 25226613, 2014). "TIMP-3 acts as a tumor suppressor and inhibitor of angiogenesis, and Timp-3 homozygous-null mice present with enhanced TNF signaling and serum IL-6 levels, indicating a key role for TIMP-3 in innate immunity." (PMID 25606593, 2014). "The only pro-angiogenic genes found up-regulated, and substantially, were that coding the chemokine IP-10/CXCL10 which was also strongly expressed in vivo by PC3 tumor from IL-27 treated animals, and the metalloproteinase inhibitor, TIMP3, in DU145 cells." (PMID 24681516, 2014). "The TIMP3 gene acts as a tumor suppressor in some cancers by affecting tumor growth, angiogenesis, invasion and the development of metastases." (PMID 23527119, 2013). "For this purpose, we used a lentiviral expression system to generate stably transduced TIMP3-overexpressing tumor cell clones." (PMID 23894681, 2013). "Loss of TIMP3 expression correlates with poor prognosis, supporting the involvement of TIMP3 in preventing tumor metastasis." (PMID 23527119, 2013). "Several represented genes, TIMP3, p16 (CDKN2A), p14, MGMT, CDH1, RASSF1A and DAPK, are highly sensitive to methylation-induced repression in HNSCC tumor and saliva samples, and are directly associated with tumor development." (PMID 25587491, 2013). "Among all, the most interesting features of TIMP3 are the inhibition of tumor cell invasion and the potent proapoptotic effect on tumor cells in vivo." (PMID 23894681, 2013). "TIMP3 and CCNA1 hypermethylation was significantly associated with lower rates of second primary tumor-free survival (p = 0.007 and p = 0.001; log-rank test, respectively)." (PMID 24359512, 2013). "Croce and his group (2009) described an increase of miR-221 and -222 in NSCLC and HCC through c-JUN induction and PTEN and TIMP3 tumor-suppressor targeting." (PMID 21711453, 2011). "Induction of functional TIMP-3 in TIMP-3-deficient human DLD-1 colon cells shows a growth arrest and inhibits tumor growth in vivo." (PMID 21859479, 2011). "Like Txnip and Zbtb16, Timp3 has tumor-suppressive properties, and its expression limits tumor invasiveness and has been correlated with survivorship in cancer patients." (PMID 19968875, 2009).
tumor (continued). "Many human tumor samples also gained expression of a coordinately regulated module associated with advanced malignancy (ABCC1, FOXO3A, LIF, PIK3R1, PRNP, TNC, TIMP3 and VEGF)." (PMID 17615082, 2007). "This is in accord with the observation that overexpression of TIMP-3 in tumor cells inhibits invasion, a function consistent with its role as an MMP inhibitor, and induces apoptosis in vitro." (PMID 17032447, 2006). "This is the first immunohistochemical study to show that, of the two tissue localizations of TIMP-3 protein, cancer and stromal, the one within the cancer cells seems to have a more active role in the modulation of tumor phenotype." (PMID 17032447, 2006). "We found TIMP-1, TIMP-2 and TIMP-3 to be highly expressed both in normal tissue and in tumour tissue, with increased expression in high-grade tumours." (PMID 16465195, 2006). "In other words, according to our findings, reduced TIMP-3 expression seems to be related to cell cycle deregulation and tumor cell proliferation, further contributing to the development of an aggressive tumor phenotype." (PMID 17032447, 2006). "Studies on silencing of TIMP-3 by gene methylation also suggested a tumor suppression role in several malignancies." (PMID 17032447, 2006). "This is the first study to report a relationship between TIMP-3 expression and the grade of tumor differentiation." (PMID 17032447, 2006). "TIMP-3, which emerges as one of the most consistently tumour inhibitory TIMPs, can promote apoptosis by its selective effects on ADisintegrin And Metalloproteinase (ADAM)-mediated shedding of death-domain containing receptors." (PMID 15928670, 2005). "It was apparent from this paired comparison that nearly all tumours with methylation in E-cadherin, hMLH1 and TIMP3 had methylation detected in the serum DNA as well." (PMID 15942635, 2005). "The expression of TIMP-3 protein was localised in shallow areas of the tumour, and was reduced in deep areas of the same tumour." (PMID 15467768, 2004). "Immunostaining of TIMP-3 was seen in the cytoplasm of cancer cells and normal oesophageal epithelial cells, particularly in cells located in shallow areas of the tumour." (PMID 15467768, 2004). "Other functions of TIMP-3 have been reported, including suppression of tumour growth and angiogenesis." (PMID 15467768, 2004). "Significant correlations were observed between TIMP-3 expression and depth of tumour invasion (P=0.001), number of lymph node metastases (P=0.003), infiltrative growth pattern (P=0.003), and disease stage (P=0.005)." (PMID 15467768, 2004). "Our immunohistochemical results suggest that expression of TIMP-3 protein is correlated with depth of tumour invasion, the number of lymph node metastases and disease stage." (PMID 15467768, 2004). "It is thought that, in contrast to epithelial markers, such as plakoglobin or cytokeratins 18 and 19, mesenchymal markers, TIMP-2, TIMP-3, thrombospondin-1 and/or α1VI/α2I integrins may predict the invasive and metastatic phenotype of tumour cells." (PMID 40724562, 2025). "While the clinical relevance of TIMP3 expression in malignant tumors has been extensively studied, its relationship with tumor-infiltrating lymphocytes and cancer prognosis remains unclear." (PMID 41009435, 2025). "Taken together, we can infer that the expression of TIMP3 correlates with the suppression of tumor immune infiltration, which may be relevant to the immunotherapy of tumors." (PMID 40357367, 2025). "However, the overexpression of mirtron hsa-mir-877–5p in TNBC cells downregulates TIMP3, thereby promoting tumor metastasis." (PMID 40861257, 2025).